MT1X (metallothionein 1X)
Diseases named in the same sentence as MT1X in open-access papers (continued):
Sharing a sentence is not in itself a finding about the gene and the disease.
tumor (25 papers, 2015 to 2025). "CXCR4, a receptor of CXCL12, was also positively correlated with MT1X and is associated with tumor cell angiogenesis and proliferation." (PMID 36149322, 2022). "It is suggested that the MT1X gene in the lysosomal pathway may be associated with the proliferation and growth of tumour cells." (PMID 37091857, 2023). "An examination of mRNA levels within the TCGA-GTEx cohort demonstrated a notable increase in KLK10, LAMA3, MET, KRT7, and SFTA2, alongside a decrease in MT1X in tumor samples compared to their normal counterparts." (PMID 38893622, 2024). "Cluster Fib_6 cells exhibited high expression of MT1-related genes (MT1E and MT1X) that activate tumor-suppressing immune cells." (PMID 37533434, 2023). "MT1X is a member of the metallothionein (MT) family, which controls metal ion homeostasis to influence tumor growth, progression, metastasis, and drug resistance." (PMID 37188204, 2023). "The results showed that MT1X gene expression was weaker in tumour cells than in paraneoplastic tissues in most tumour types, except CESC, GBM, UCEC and LUSC." (PMID 37091857, 2023). "In cellular experiments, qPCR and flow cytometry were used to assess the role of the lysosomal pathway gene-MT1X on tumour cell development." (PMID 37091857, 2023). "At the beginning of the present study, we used Oncomine and TIMER to confirm the different expression levels of MT1X between normal and tumor tissues from human cancers." (PMID 36149322, 2022). "All results above suggest that ccRCC patients with high expression of MT1X are more liable to have tumors in high tumor stage and grade and more likely to have distant metastasis." (PMID 36149322, 2022). "MT1X was demonstrated to be a tumor suppressor that suppresses tumor growth and metastasis in vivo and induces cell cycle arrest and apoptosis by repressing the NF-κB signaling pathway in HCC." (PMID 35300417, 2022). "The TISIDB database analysis showed a significant correlation between MT1X and tumor-infiltrating lymphocytes such as central memory CD8+ T cells and γΔT cells." (PMID 36149322, 2022). "Examination of the spatial distribution across the tumor sections revealed a sarcosine-related decline of the MT1X isoform within the marginal regions but an elevation after antisarAbs@LIP administration." (PMID 27646588, 2016). "We further found that high MT1X expression is related to distant tumor metastasis." (PMID 36149322, 2022). "MT1X is considered as a tumor inhibitor, and is involved in the progression and metastasis of HCC." (PMID 36466860, 2022). "Accordingly, MT1X could be a potential biomarker that distinguishes tumor tissues from normal tissues and predict the prognosis of ccRCC." (PMID 36149322, 2022). "Besides regulation of mast cells, MT1X was aslo found to be significantly related to cell hypoxia, which OS is an essential factor in tumor progression and distant metastasis." (PMID 36149322, 2022). "Besides, the differential expression of MT1X in ccRCC versus normal kidney tissues may also permit us to distinguish normal tissue from the tumor, which may be used as a detection index for tumor screening." (PMID 36149322, 2022). "Consequently, MT1X’s connection with TGFB1 may contribute to the malignant behavior of ccRCC tumor cells." (PMID 36149322, 2022). "According to our wound healing assay, knockdown of MT1X inhibited cell migration, which is consistent with the bioinformatic results that ccRCC patients with high expression of MT1X are more liable to have tumors in high tumor stage and grade and more likely to have distant metastasis." (PMID 36149322, 2022). "We also add this result in part GO enrichment analysis showed that MT1X was involved in regulating and responding to metal ions, such as zinc, copper, and cadmium, which are proved to be important factors to the immune system and affect the tumor immunotherapy." (PMID 36149322, 2022).
tumor (continued). "Therefore, the four MT1s (MT1G, MT1E, MT1F and MT1X) are down regulated in tumor samples, at the same time, they are also down regulated in tumor samples with MT1 deletion, indicating that MT1 deletion may affect the expression of its genes in HCC." (PMID 34257549, 2021). "However, MT1X was identified as a tumour suppressor involved in HCC progression and metastasis." (PMID 33215860, 2021). "qRT-PCR revealed significant upregulation of CXCL10, CXCL11, ME1, MT1X, FAT1, OAS2, and MT2A in tumor tissues compared to normal tissues." (PMID 40574841, 2025). "Knockdown of MT1X in the setting of hypoxia reduces the accumulation of HIF-1α, EPO, VEGF, and CA9, which are important factors that regulate tumor cell adaptation to hypoxia (P<0.05)." (PMID 36149322, 2022). "Using logistic regression, MT1X expression conspicuously correlated with patient age (P=0.0156), T (T1 vs. T4, P=0.0487), grade (II vs. IV, P=0.0145; III vs. IV, P=0.0005), primary tumor laterality (P=0.0432) and person neoplasm status (P=0.0008)." (PMID 36149322, 2022). "Compared with the sensitive group, MT2A, MT1E, MT1X expression were down-regulated in immune-resistant patients, and were correlated with the infiltration of various immune cells, including CD8+ effector T cells, in tumor tissues." (PMID 36466860, 2022). "The results of some experiments showed that miR-376a-3p could target the downregulation of MT1X in the AML cell line, predicting that it might be as a tumor depressor regulating the process of AML." (PMID 35316152, 2022).
cancer (19 papers, 2012 to 2025). A tumor composed of atypical neoplastic, often pleomorphic cells that invade other tissues. "As the key protein of anti-apoptosis, MT1X plays a vital roles in the proliferation of cancer cells." (PMID 35316152, 2022). "Using TIMER, we found that MT1X was down-regulated by 17 human cancers and up-regulated in five types of cancer." (PMID 36149322, 2022). "Finally, as a demonstration of the ability of TEPA to reduce intracellular copper levels in cancer cells, we observed a robust reduction in MT1X expression, a metallothionine used as a surrogate measure of intracellular levels of copper, by real-time PCR." (PMID 37480151, 2023). "Excepting differences in data collection and analysis methods between studies, the different expressions of MT1X in different cancers may be illustrative of the different biological properties of these tumors." (PMID 36149322, 2022). "Knocking down TCRP1 and MT1X by siRNA could sensitize cells to cisplatin through increased cancer cell apoptosis and inhibition of cell proliferation." (PMID 23251525, 2012). "Next, the correlation between MT2A, MT1E, MT1X expression and CD8+ T cells and other immune cells in various malignant tumors was analyzed by bioinformatics database." (PMID 36466860, 2022). "To gain further insight into the biological functions of MT1X, we used the human VHL defective ccRCC line 786O to detect some of the genes typically targeted by cancer therapies that are a part of the hypoxia pathway." (PMID 36149322, 2022). "Strikingly, members of the metallothionein family, including MT1M, MT1H, MT1G, MT1F, MT1E, MT1X, and MT1A, were significantly downregulated in cancer cells." (PMID 35967424, 2022). "In contrast the expression of MT1X, MT2A, IL10RA, KIT was lower in cancer tissues as compared to normal tissues." (PMID 33240582, 2020). "While down-regulated genes were associated with GO categories such as cellular response to zinc ion where members of metallothionein family (MT1M, MT1H, MT1X, MT1G, and MT1F) play important roles in carcinogenesis of various cancer types." (PMID 32849813, 2020). "We identified 15 highly connected hub genes in MEtan, including ABCA8, AFP, EGR3, EXO1, HMGA1, MT1X and VARS, which play roles as major regulators in cell-cycle regulation and cancer development." (PMID 27220887, 2016). "Conversely, some genes that displayed anti-HIV activity are known to be involved in signaling, both in various cancers (CD164, TNFRSF10A/D, ZWINT, MT1X, IL3) and immune or T cell activation (GBP5, CD1A)." (PMID 25980612, 2015). "A majority of cuproptosis-related genes like CP, MT1E, MT1F, MT1X, VEGFA, and PDK1 were expressed significantly higher on cancer cells, indicating that cuproptosis might occur mainly on cancer cells." (PMID 36211378, 2022). "Additionally, we found that nearly half of these 21 edges involved a protein of the Metallothionein family (i.e. MT1H, MT2A, MT1HL1, MT1X and MT1G), involved in the regulation of transcription factors and in cancers." (PMID 34197603, 2021). "In summary, by establishing a link between MT-1X and FHL3, this study highlights MT-1X as a potential candidate for investigating the molecular mechanisms of cancer cell anti-apoptotic activity and also novel useful molecular targets for cancer therapy." (PMID 24690879, 2014). "In addition, as clearly shown in the volcano plot, the presence of dysregulated genes required in copper homeostasis (MT1X, MT2A) might reflect the cancer cell’s response to AgNPs." (PMID 40076651, 2025).
infection (1 paper, 2020). The state of being infected such as from the introduction of a foreign agent such as serum, vaccine, antigenic substance or organism. "Response to stress (MT1X), repair process (DCLRE1A), and T cell activation-related genes (B2M) were the most important upstream regulators during the decline phase of the gt3 infection." (PMID 32877413, 2020).
MT1X also shares sentences with these, for which no sentence is quoted: mental retardation (2 papers); acute myeloid leukemia (1); Alzheimer disease (1); amyloidosis (1); atopic dermatitis (1); cardiac hypertrophy (1); colon cancer (1); colorectal cancer (1); colorectal tumor (1); diabetes (1); diffuse large B-cell lymphoma (1); Down syndrome (1); glioblastoma (1); head and neck squamous cell carcinoma (1); infectious disease (1); invasive ductal carcinoma (1); liver cancer (1); malaria (1); melanoma (1); metabolic disorder (1); neurological disorders (1); nutritional deficiency (1); renal carcinoma (1).